EGFR (epidermal growth factor receptor)
Diseases named in the same sentence as EGFR in open-access papers (continued):
Sharing a sentence is not in itself a finding about the gene and the disease.
tumor (continued). "With evidence of safe bypassing of the BBB, it is of note to consider targeting tumor cells based on the biology e.g., EGFR and/or VEGF positive." (PMID 36833093, 2023). "Cetuximab, a chimeric IgG1 antibody against EGFR, can evoke a T-cell-mediated anti-tumor immune response and stimulate NK-mediated antibody-dependent cellular cytotoxicity, independently of RAS mutational status." (PMID 36765821, 2023). "Our results revealed that high TMB, EGFR mutation, and TERT mutation had a significant association with tumour recurrence in NMIBC." (PMID 37892022, 2023). "The deletion polymorphisms or low levels of messenger RNA (mRNA) of the proapoptotic Bcl-2 family member, BIM, enabled the tumor to resist the apoptosis effects of EGFR-TKI." (PMID 36902280, 2023). "The abnormal elevated expression and activity of EGFR in NSCLC are frequently associated with poor prognosis, increased tumor growth, metastasis, and resistance to various cancer therapies." (PMID 37438719, 2023). "Blocking EGFR or ICAM-1 in TAM by drugs or antibodies inhibits tumor tissue formation and disease progression in mouse models of ovarian." (PMID 37005667, 2023). "They evaluated several antibody formulations targeting EGFR (expressed on tumor cells) to redirect and increase the macrophage phagocytosis rate by a process known as antibody-dependent cell phagocytosis." (PMID 38106674, 2023). "EGFR is known to play a critical role in maintaining tumor cell survival through its downstream signaling that rely on its kinase activity." (PMID 37178919, 2023). "New targeted fluorophores can bind to tumor-specific markers such as the epidermal growth factor receptor (EGFR) and other peptides." (PMID 37835584, 2023). "The EGFR signaling pathway recruits TAMs and MDSCs, converting M1-like TAMs to tumor-promoting M2-like phenotype, which further induce T cell and NK cell dysfunction." (PMID 37601668, 2023). "As the affinity of cetuximab for EGFR is nearly 5 to 10 times of the endogenous ligands, it can block endogenous ligand binding, which reduces EGFR-mediated signaling and leads to growth inhibition of tumor cells." (PMID 37055797, 2023). "In two of the highest-lift item-sets for predicted EGFR mutant status, fibrosis is present alongside the tumor-related features." (PMID 36927889, 2023). "EGFR-amplified tumours that switched subtype switched in three cases from classical to mesenchymal subtype, two cases from mesenchymal to classical subtype, and one case switched from proneural to classical subtype." (PMID 36765632, 2023). "Overexpression of EGFR has been reproducibly detected in a large number of tumor samples and found to act as a strong prognostic indicator in head and neck, ovarian, cervical, bladder and esophageal cancers, correlating to poorer survival rates." (PMID 36839989, 2023). "Previously, we reported that dual targeting EGFR with a monoclonal antibody (cetuximab) and TKI (afatinib or osimertinib) led to sustained tumor control in patients with EGFR 20ins-positive NSCLC9,10." (PMID 37308490, 2023). "The inactivation of these adaptor proteins, which regulate both the duration and intensity of EGFR signaling, plays an important role in tumor proliferation." (PMID 37576898, 2023). "Tumor mutational load (TMB), epidermal growth factor receptor (EGFR) mutations, and soluble programmed cell death ligand-1 (sPD-L1) can predict response to immunotherapy." (PMID 37036321, 2023). "Patients with EGFR-mutated NSCLC lack T-cell infiltration and have decreased ratios of PD-L1+/CD8+ tumor-infiltrating T cells." (PMID 37033978, 2023). "For example, stabJGL identifies phosphorylated epidermal growth factor receptor (EGFR) as a central hub protein in all three tumor types." (PMID 38152341, 2023).
tumor (continued). "We show that these tumours have recurrent and mutually exclusive mutations in either ACVR1 or EGFR and are characterised by high expression of EZHIP associated to its promoter hypomethylation." (PMID 36882456, 2023). "Heterogeneity was also observed within 13 clones from another tumor in which one had EGFR amplification and the rest were balanced/wild type." (PMID 38136371, 2023). "In our recent publication, we have shown that the genetic deletion of a single ligand of the ERBB family, BTC, also led to a reduced tumor burden in Kras mice, which was due to decreased EGFR‐signaling." (PMID 37341059, 2023). "In this study, our results support that AnxA6 SUMOylation at K299 residue facilitates the binding of PKCα to EGFR and subsequently enhances its tumor-suppressor activity in vitro and in vivo." (PMID 37528485, 2023). "Anti-cancer efficacy against EGFR mutant tumours has been shown in large-scale clinical investigations in patients with NSCLC, which were inspired by positive findings from pre-clinical research." (PMID 37375846, 2023). "HCD3514 treatment revealed a significant inhibition of phosphorylation of EGFR in tumor xenografts, supporting that the antitumor efficacy of HCD3514 was through the inhibition of AZD9291-resistant EGFR mutations." (PMID 36605493, 2023). "Specifically, we investigated the combinatorial effects of these bioengineered OMVs, which involved EGFR inhibition and localized immune activation, and examined their impact on tumor growth." (PMID 37775519, 2023). "It was discovered that intravenous administration of recombinant OV HSV1716EGFR, which can express anti-epidermal growth factor receptor (EGFR) scFv, increased the accumulation of virus in tumor tissue by 8-fold 24 days following injection." (PMID 36835091, 2023). "Improved survival and smaller tumour size in an hCD89+ mouse tumour model demonstrated a therapeutic gain of the chimera over the parental EGFR-specific IgG and IgA." (PMID 36817447, 2023). "MMR/MSI status and EGFR expression showed sex-specific molecular features when stratified according to tumor location." (PMID 36802389, 2023). "Proteolysis-targeting chimeras (PROTACs) that target EGFR for degradation are being explored and show good anti-tumor responses in pre-clinical studies." (PMID 37174055, 2023). "Although many tumours show an initial response to the treatment with EGFR inhibitors, resistance to treatment often occurs due to point mutations in the ATP binding pocket of EGFR, such as T790M, L858R, and C797S." (PMID 37038884, 2023). "The combination of amivantamab and lazertinib, targeting EGFR at both its extracellular and catalytic domains, was shown to have synergistic inhibition of tumor growth in preclinical." (PMID 37296863, 2023). "Epidermal growth factor receptor (EGFR) is highly expressed in different tumor-types but presents a specificity challenge, as it is also found in normal tissues." (PMID 36831591, 2023). "In fact, knocking-down or pharmacological inhibition of TMEM16A/ANO1 in tumor cells inhibited their proliferation by reducing EGFR activation and its downstream signaling pathways." (PMID 36979639, 2023). "Transgenic PKT mice (Ptf1aCre/+; LSL-KrasG12D/+; Tgfbr2flox/flox) were used for in vivo studies to examine tumor volume with the pancreas and overall survival of combined Src and EGFR inhibition." (PMID 36902166, 2023). "Unfortunately, acquired resistance still develops in patients after EGFR-TKIs treatment, leading to tumour recurrence and metastasis." (PMID 37156816, 2023). "Our results demonstrate that incorporating the EGFR-targeting Ab Cmab improved MSC binding to immobilized EGFR protein and to tumor cells overexpressing EGFR." (PMID 37376189, 2023). "Because of the comparatively low affinity of HCP-LCE to EGFR, increased target expression, which is predominantly found on tumor cells, is required for targeting of the antibody." (PMID 37081888, 2023).
tumor (continued). "In tumor patients, pro-inflammatory cytokines can induce cellular senescence by activating EGFR signaling; this is inhibited by Gefitinib, a small-molecule inhibitor of EGFR." (PMID 37340393, 2023). "In this study, we tried to characterize the role of EGFR and its homeostasis in cultured endometrial mesenchymal stromal cells isolated from menstrual blood in comparison with tumor-derived HeLa cells." (PMID 37686213, 2023). "The development of an antibody-guided LIGHT (anti-EGFR-hmLIGHT fusion protein) was shown to enhance TIL entry into EGFR-expressing Ag104Ld tumours." (PMID 37287625, 2023). "To determine in vivo anti-tumor efficacy we tested the EGFR (n=4), HER2 (n=4), and mesothelin (n=3) T-BsAbs in an intraperitoneal model of DSRCT (JN-DSRCT-1-luc), which more closely recapitulates human disease than a standard flank xenograft." (PMID 37091153, 2023). "Our findings, taken together, suggest that in HNSCC, the inhibition of both β2-AR and EGFR signaling is a potential target to strongly reduce tumor cell growth." (PMID 37723219, 2023). "Inhibiting only a part of the MAPK pathway (BRAFi or MEKi in monotherapy) triggers a feedback loop that leads to EGFR hyperactivation and subsequent tumor growth." (PMID 37958416, 2023). "The robustness of our method in tumor fluorescence extraction has been validated through PLGA-anti-EGFR fluorescence imaging experiments on 10 mice." (PMID 36998445, 2023). "The combination of EGFR inhibitors with RT has a synergistic effect because RT increases EGFR expression in tumor cells, and blocking EGFR can make cells more sensitive to radiotherapy." (PMID 38074690, 2023). "Cetuximab represents an IgG1 monoclonal antibody against the ligand-binding domain of the abnormally activated and overexpressed epidermal growth factor receptor (EGFR), thus down-regulating tumor growth and improving the cytotoxic effect of radiation." (PMID 37685806, 2023). "In summary, the GSEA results suggested image-derived tumor-tumor interaction as a biomarker for EGFR TKI responsiveness." (PMID 36647832, 2023). "EGFR-dependent tumours through the EV cargo of specific proteins, mRNAs, or miRNAs can modulate long-distance and organ-specific cells by promoting growth and invasion, regulating TME, and conferring drug resistance." (PMID 37296932, 2023). "In conclusion, Afatinib as a single-agent neoadjuvant therapy for stage III EGFR-mutant NSCLC offers a favorable objective tumor response and has an acceptable toxicity profile in clinical practice." (PMID 37537219, 2023). "In this study, we aimed to investigate the mechanism by which Feiyiliu Mixture delays osimertinib resistance in EGFR-mutant cell lines and EGFR-mutant cell tumor-bearing mice." (PMID 36744262, 2023). "In other words, our criteria did not necessarily select the patients with sufficient amount of tumor cells with EGFR amplification to derive clinical benefit from GC1118." (PMID 37537946, 2023). "Cyclin D1 was observed in 40% of cases in adjacent non-tumour liver, while EGFR and VEGF were detected in 88.9% and 61.1%, respectively." (PMID 38414954, 2023). "When expressed and activated in tumor cells, EGFR stimulates the production of interleukins, which have been shown to encourage angiogenesis within the tumor." (PMID 37895416, 2023). "The combined activation of EGFR and Hh pathway synergistically promote tumor formation, in part due to EGFR-GLI regulated RAF/MEK/ERK target JUN/AP-1 expression." (PMID 37853413, 2023). "Unfortunately, EGFR-targeted therapy also favors the emergence of drug tolerant or resistant cells, ultimately resulting in tumor relapse." (PMID 36672453, 2023). "This study not only highlighted the association between imaging features and tumor phenotype but also explored changes in imaging features before and after targeted therapy in NSCLC patients with different EGFR mutation statuses." (PMID 38027000, 2023).
tumor (continued). "In our study, a moderate sensitivity of 69.2% was achieved for identifying plasma EGFR mutations via both cfDNA assays, consistent with previous studies, which suggests that plasma EGFR mutations might be highly predictive of identical mutations in corresponding tumor tissues." (PMID 37372399, 2023). "Three of forty patients in the study cohort had EGFR-amplified tumours and received targeted EGFR therapy." (PMID 36765632, 2023). "Deficient Egfr in murine myeloid cells decreased carcinogenesis, suggesting a tumor-promoting function by myeloid cell-intrinsic EGFR signaling." (PMID 38001917, 2023). "The delivery of ectopic miR-145-5p through the development of miRNA-145-based magnetic nanoparticle formulation downregulated oncogenic targets such as MUC1, OCT4, and EGFR, thereby efficiently inhibiting tumor growth and metastases in mice." (PMID 37598177, 2023). "In the current study, median OS among patients with left-sided versus right-sided tumours (15.3 vs 10.6 months) aligns with previous reports of longer survival in those with left-sided tumours treated with anti-EGFR therapies." (PMID 37919668, 2023). "By analyzing patient clinical outcomes with image features, a higher tumor-tumor interaction was found to correlate with higher benefit from EGFR TKI, while a higher tumor-stroma interaction correlated with less benefit from EGFR TKI." (PMID 36647832, 2023). "nEGFR is a major driver of tumor progression, metastasis, and resistance to anti-EGFR therapies and has been suggested to be a better biomarker than total cell EGFR levels." (PMID 37720348, 2023). "Future investigations should focus on the influence of EGFR signaling blockade on tumor immunity and survival using the MEC cell lines." (PMID 36675234, 2023). "This tumor specificity is in stark contrast to the roles of EGFR’s kinase domain which are critical in a majority of human tissues at nearly all developmental stages." (PMID 37720348, 2023). "HGF secretion is predominantly attributed to stromal cells, but tumor-derived HGF has also been reported in EGFR TKI-resistant tumor cells." (PMID 36647832, 2023). "Further immunohistochemical staining confirmed the inhibition of LCN2 expression in the NPs-siLCN2 group, and the levels of p-EGFR and the tumor proliferation index Ki67 were also decreased." (PMID 36899380, 2023). "Subsequent analyses uncovered tumor-cell-intrinsic mechanisms such as induction of apoptosis and downregulation of p-EGFR, p-AKT, p-ERK, and p-RAS40 levels, which underlie the synergistic anti-tumor activity of erlotinib+MLN0128." (PMID 36831214, 2023). "A prime example concerns the eligibility for anti-EGFR treatment, where the RAS mutation status of tumor tissue must be determined prior to formulating a treatment plan." (PMID 36831626, 2023). "In summary, PSAT-IQGAP1-STAT3 is upregulated in erlotinib-resistant cells, and PSAT1 promotes tumor metastasis and EGFR inhibitor resistance." (PMID 37381723, 2023). "The EGFR protein was pivotal in inducing tumor promotion and in impeding apoptosis in cancer cells by inducing phosphorylated AKT serine/threonine kinase 1 (pAKT) and nuclear factor kappa B (NFκB)." (PMID 38139811, 2023). "LRIG1, a transmembrane protein that negatively impacts the epidermal growth factor receptor (EGFR) signaling pathway, plays a role in tumor development when its function is disrupted." (PMID 37936192, 2023). "In preclinical studies, DS‐1205c restored TKI antitumor activity in a TKI acquired‐resistance EGFR‐mutant NSCLC tumor xenograft model." (PMID 36621830, 2023). "In this study, the serum levels of ERBB2 and NRG4, which are involved in the EGFR signaling pathway, correlated with tumor characteristics." (PMID 37174100, 2023). "When incubated with tumor cells, EGFR CAR-E27-CCR6 T cells specifically exerted potent cytotoxicity and produced high levels of pro-inflammatory cytokines, including tumor necrosis factor-α (TNF-α), interleukin-2 (IL-2), and interferon-γ (IFN-γ)." (PMID 36982500, 2023).
tumor (continued). "In vitro experiments confirmed that the co-culture system of EGFR-mutant tumor cells with immune cells was able to reduce the viability of tumor cells after treatment with PD-1 inhibitors." (PMID 37869096, 2023). "The epidermal growth factor receptor (EGFR) is an oncogenic tyrosine kinasethat is involved in tumor initiation and progression, making EGFR inhibitorsand monoclonal antibodies to this receptor essential for anti-tumor therapy." (PMID 37538799, 2023). "Knockdown of GSDMD inhibits tumor growth through promoting the mitochondrial apoptotic pathway and inhibiting epidermal growth factor receptor (EGFR)/AKT signaling." (PMID 36932407, 2023). "A study found that the metastatic phenotypes of tumor cells are promoted by constitutively active forms of EGFR." (PMID 36831661, 2023). "Inhibition of xCT with chemical drug sulfasalazine induces apoptosis in CD44v-positive HNSCC cells in murine xenograft models and sensitizes tumor cells to the epidermal growth factor receptor (EGFR)-targeted therapy with cetuximab." (PMID 37823053, 2023). "The TGN-PEG-P75 had uniform edge length (77.9 ± 7.0 nm), a neutrally charged surface, and a high affinity to EGFR-expressing cells via P75, with subsequently increased accumulation at the tumor site." (PMID 37754880, 2023). "Univariate analyses revealed a significant association of TMB, EGFR mutation, and TERT mutation with tumour recurrence within 1 year (p = 0.030, p = 0.033, and p = 0.039, respectively)." (PMID 37892022, 2023). "These promising preclinical findings suggest that EGFR-targeted nanotherapy has the potential to improve NSCLC treatment through enhanced tumor targeting, cytotoxicity, and overcoming resistance." (PMID 37754880, 2023). "MTSS1 downregulation in tumor cells resulting from EGFR–KRAS activation stabilizes PD-L1 and enhances immune evasion." (PMID 36810288, 2023). "For these tumour types, therapies targeting EGFR, ERBB2, or their downstream effectors such as MEK or PI3K have shown some degree of success." (PMID 38041118, 2023). "EGFR is upregulated as a result of mutations in 4% to 66% of patients with HCC and is involved in tumor angiogenesis and proliferation." (PMID 36043445, 2023). "W2014-S, a novel STAT3 inhibitor, can significantly enhance the anti-tumor effect of EGFR-TKIs in TKI-resistant NSCLC." (PMID 37649478, 2023). "Combining other anti-cancer drugs including DOX (20 μg/mL), liposomes (1.5 μg/mL) and mAbs Bevacizumab (1 mg/mL) with anti-EGFR-iRGD VHHs significantly enhanced their penetration capability and tumor inhibiting activity in mice models." (PMID 37746282, 2023). "Another example is Amivantamab, a bsAB targeting EGFR and c-Met driving tumor growth in patients with non-small cell lung cancer (NSCLC)." (PMID 36900399, 2023). "EGFR activates numerous downstream signaling molecules that promote cell proliferation, survival, and tumor progression." (PMID 38077251, 2023). "In normal cells, the expression of EGFR is estimated to be from 40,000 to 100,000, whereas in tumor cells, more than 106 receptors per cell are overexpressed." (PMID 38201528, 2023). "Currently, the clinical efficacy of savolitinib is being investigated in several tumours and EGFR+ NSCLC that progress to osimertinib and develop MET OE/MET AMP." (PMID 37835473, 2023).